LINC01023 (long independently transcribed non-coding RNA 1023)
Gene: Long non-coding RNA gene on chromosome 5 (108,725,707 to 108,728,744, reverse strand). Ensembl gene ENSG00000272523.
Diseases named in the same sentence as LINC01023 in open-access papers:
LINC01023 is named in the same sentence as 2 diseases in open-access papers, as found by Europe PMC text mining. Sharing a sentence is not in itself a finding about the gene and the disease. The quoted sentences say what the papers report.
brain cancer (1 paper, 2023). A primary or metastatic malignant neoplasm affecting the brain. "Interestingly, oncogenic role of LINC01023 has been described in liver and brain cancers." (PMID 36625266, 2023).
glioma (1 paper, 2019). A benign or malignant brain and spinal cord tumor that arises from glial cells (astrocytes, oligodendrocytes, ependymal cells). "LINC01023 is a regulator of the IGF1R/Akt pathway in glioma, again a signaling pathway that has been shown to regulate CF lung disease." (PMID 31842871, 2019).